TFE3 (transcription factor binding to IGHM enhancer 3)
Diseases named in the same sentence as TFE3 in open-access papers (continued):
Sharing a sentence is not in itself a finding about the gene and the disease.
tumor (227 papers, 2009 to 2026). "Specifically, TFE3 upregulates genes associated with the transforming growth factor-beta (TGFβ) pathway, thereby altering the tumor microenvironment." (PMID 41446840, 2025). "Morphologic and molecular parameters associated with poor outcome include large tumor size, high mitotic index, necrosis, nuclear atypia, infiltrative growth, and the presence of TFE3 rearrangements." (PMID 41463261, 2025). "In luminal breast cancer, the loss of FLCN activates TFE3, which then induces pathways promoting tumor growth, such as autophagy, lysosome biogenesis, aerobic glycolysis, and angiogenesis." (PMID 40143966, 2025). "By identifying markers linked to tumor aggressiveness, such as TFE3 and Vimentin, clinicians can tailor monitoring and therapeutic interventions, optimizing outcomes for patients with this rare RCC subtype." (PMID 39851801, 2025). "Some specialists consider strong TFE3 staining intensity in more than 75% of tumor cells as diagnostic." (PMID 39206137, 2024). "Previous studies have shown that TFE3 fusion protein is associated with tumour progression by promoting its nuclear translocation." (PMID 38104198, 2023). "Significant tumor-growth inhibition in vivo by ASPSCR1::TFE3 loss indicates the importance of co-proliferation between tumor cells and blood vessels in ASPS." (PMID 37029109, 2023). "Results of the present study demonstrated that the expression of TFE3 in RCCs was significantly associated with higher nuclear grade, tumor stage, and metastasis." (PMID 36276115, 2022). "Multiple autophagy-associated signaling pathways are regulated by the TFE3 gene, thereby influencing tumor growth." (PMID 36276115, 2022). "The tumor mutation burden (median 0.28, range: 0–4.76) in our TFE3-tRCC cohort was lower than that of KIRC and KIRP in TCGA cohort." (PMID 34489456, 2021). "ASPS was selected for validation studies because its characteristic hallmark TFE3 genetic rearrangement allows for unambiguous identification of tumor cells enriched from blood samples with the ApoStream® device." (PMID 28403214, 2017). "Immunohistochemically, except for molecular genetic analysis, nuclear reactivity of TFE3 protein is the most sensitive and specific method for TFE3 rearrangement-associated neoplasm." (PMID 28949976, 2017). "An essential diagnostic marker in this unusual presentation of neoplasm is the nuclear over-expression of TFE3 as well as ultrastructural study, which reveals the presence of peculiar cytoplasmic crystalline inclusions." (PMID 26837430, 2016). "This FISH assay can be utilized as an adjunct to morphology and immunohistochemistry to diagnose TFE3-associated carcinomas and other neoplasms." (PMID 26415891, 2015). "As in previous cases, the tumor described here demonstrated diffuse TFE3 nuclear staining and an underlying TFE3 rearrangement was confirmed by break-apart FISH assay." (PMID 24735727, 2014). "The ASPSCR1-TFE3 fusion gene is believed to cause aberrant activation of TFE3, which is thought to promote angiogenesis, cell proliferation, differentiation, and inhibiting apoptosis, thereby potentially contributing to tumorigenesis and tumor progression." (PMID 41446840, 2025). "Moreover, TFEB and TFE3 exhibit overlapping functions and are implicated in genetic rearrangements that regulate DNA damage, proliferation and drive the formation of tumor cell 52-54." (PMID 38481802, 2024). "Therefore, TRIM63 RNA-ISH staining would be expected in not only TFE3 fusion-associated neoplasms (like ASPS) but also in some non-TFE3-fused neoplasms." (PMID 38393424, 2024). "Immunohistochemistry showed TFE3(+), Ki67(about 8%+), S-100(focal+), CD68(portion+), TTF-1(‐), AE1/AE3(‐), HMB45(‐), P40(‐), SMA(‐), Desmin(‐), CA-IX(+), IN-1(+), and SMARCA4(+), suggesting that the tumor could be associated with TFE3 gene translocation." (PMID 39495972, 2024).
tumor (continued). "A selective growth-inhibitory effect of Mithramycin A has been observed in FLCN-deficient tumor cells as well,which are characterized by activated wild-type TFE3, suggesting that TFE3-driven tumor cells may be specifically sensitive to this drug." (PMID 37095531, 2023). "Our previous study identifies that TFE3 rRCC exerts a preference for oxidative phosphorylation, which is different from common RCCs, and nicotinamide ribokinase 2 (NMRK2) upregulated by TFE3 fusion is associated with enhanced mitochondrial respiration and tumor progression in TFE3 rRCC." (PMID 37770905, 2023). "Moreover, the positive TFE3 expression is associated with tumor progression and poor prognosis in patients with RCC irrespective of the presence of TFE3 translocation." (PMID 36276115, 2022). "Additionally, tumours are frequently associated with local lymph node metastasis and distant metastasis, and the prognosis of Xp11.2/TFE3 RCC is poorer than that of the other subtypes of RCC." (PMID 31892340, 2019). "In addition to the TFE3 rearrangement, the tumor cells showed the complete loss of SMARCB1 expression." (PMID 27733182, 2016). "Although its high sensitivity and specificity for identification of neoplasms with associated gene fusion, detection of TFE3 reactivity by IHC has been shown to be technically difficult, not inrequently accompanied with strong background stain, or even with false positive and negative results." (PMID 26369552, 2015). "Therefore, the tumor was finally diagnosed as RCC associated with Xp11.2 translocation/TFE3 gene fusion." (PMID 22738297, 2012). "Therefore, the prognosis of this tumor was affected by tumor stage, which may be associated with TFE3 expression." (PMID 29901594, 2018). "While TFE3 fusion proteins are central to its pathogenesis, their specific roles in tumor progression, particularly regarding metabolic regulation, remain incompletely understood." (PMID 41716419, 2026). "This case expands the clinicopathologic and age spectrum of YAP1::TFE3-rearranged PEComa which needs to be distinguished from other overlapping neoplasms carrying the same gene fusion." (PMID 41790187, 2026). "In vivo, subcutaneous xenografts generated by mixing tumor cells with P4+TFE3+ CAF or TFE3‐knockdown counterparts (1:2 ratio) demonstrated a significantly increased tumor volume for the P4+TFE3+ group compared to controls." (PMID 40917018, 2025). "In PTC, studies have shown that transcription factor E3 (TFE3) regulates the autophagy-lysosome pathway, driving tumor invasion and metastasis." (PMID 40493560, 2025). "The inverse relationship between ketogenesis and tumor development in our mouse models provides further insight into the metabolic adaptations in TFE3‐RCC." (PMID 39807625, 2025). "The TFE3 marker of ASPS was diffusely positive in nuclear localization in both tumor and PTC samples, indicating retention of this important molecular feature in the PTC model." (PMID 40054460, 2025). "Next, the impact of P4+TFE3+ CAF on the resistance of tumor cells exhibited under ENZ treatment was investigated." (PMID 40917018, 2025). "Taken together, these results confirm that constitutive activation of TFE3 plays a central role in driving enhanced tumor development in FlcnLiKO livers." (PMID 40189703, 2025). "Consistent with the findings at the cellular level, the oral administration of D-mannose increased the protein levels of TFE3 and Lamp1 in tumor tissues." (PMID 40259886, 2025). "In line with our previous findings, tumor areas showed strong nuclear staining for TFE3, TFEB, and SOX9." (PMID 40189703, 2025). "Strikingly, stromal TFE3 suppression showed superior efficacy to tumor‐specific HIF1A silencing, underscoring the dominance of CAF‐mediated resistance." (PMID 40917018, 2025). "Stresses promoting an MITF-to-TFEB-to-TFE3 switch will lead cells to suppress proliferation, reprogram metabolism, and impact tumor immune cell infiltration quantitatively and qualitatively." (PMID 41275493, 2025).
tumor (continued). "The mammalian target of rapamycin (mTOR) as TFE3 upstream regulator is targetable in some TFE3 rearranged tumor, like Xp11-RCC and ASPS." (PMID 39917171, 2025). "Boiling P4+TFE3+ CAF‐conditioned medium (P4+TFE3+ CAF‐CM) retained full capacity to enhance tumor sphere formation in LNCaP and 22Rv1 cells, unequivocally implicating non‐protein mediators." (PMID 40917018, 2025). "Further research is needed to determine if this phenomenon represents senescence, genomic adaptation, or tumor progression, and to explore potential interactions between TFE3 fusion proteins and hypoxia‐inducible factors in these processes." (PMID 39807625, 2025). "TFE3 rearranged EHE is still an aggressive neoplasm with a 6% (3/50) local recurrence rate and a 22% (11/50) metastasis rate, even after the surgery." (PMID 39917171, 2025). "In a breast cancer model, a low-protein diet activates the mTORC1 pathway in macrophages via TFEB and TFE3-dependent mechanisms, while inhibiting mTORC1 signaling in tumor cells, thereby slowing tumor growth." (PMID 39905317, 2025). "Immunohistochemical analysis revealed positive TFE3 staining in the tumor cells, supporting the diagnosis of ASPS." (PMID 40176092, 2025). "To further analyze the downstream mechanisms by which PRCC‐TFE3 regulates tumor development via HIF1α, we performed RNA‐seq analysis on kidney tissues from TFE3‐RCC mice." (PMID 39807625, 2025). "Our study offers new insights into the molecular mechanisms of TFE3‐RCC, highlighting the pivotal role of the PRCC‐TFE3/HIF1α/SREBP1 axis in tumor development and progression." (PMID 39807625, 2025). "Given that aberrant HIFα activation contributes to tumor development in ccRCC, our data suggest a similar role for HIFα expression in TFE3‐RCC, though it involves direct transcriptional regulation rather than effects on protein stability." (PMID 39807625, 2025). "Immunohistochemical analysis revealed a diffuse nuclear staining of tumour cells with TFE3 antibody." (PMID 38643139, 2024). "Accurate recognition of gene rearrangement is important because PEComa with TFE3 rearrangement has different tumour clinicopathological profiles and gene expression profiles than classical PEComa that closely mirror that of ASPS." (PMID 38291475, 2024). "Increasing studies have revealed that TFE3 activation is required to maintain high levels of lysosomal function which is critical for tumor growth, highlighting the potentially crucial function of TFE3 in OS biology." (PMID 37727135, 2024). "The close resemblance with other TFE3-related tumours, such as PEComa, newly described PEComa-like neoplasms or other Xp11-associated neoplasms is intriguing and suggests similar oncogenic pathways arising in different cells of origin." (PMID 38643139, 2024). "Using antibodies against both ASPSCR1 and human TFE3, we documented expression of the fusion protein in tumor lysates." (PMID 38386415, 2024). "The results of univariate and multivariate Cox proportional hazard models revealed that TFE3 rearrangement is an independent prognostic factor for recurrence, alongside tumor stage (HR = 4.6; 95% CI 1.1–21.2; p = 0.05)." (PMID 39470841, 2024). "Results of IHC on CD10, CK7 and TFE3 were concordant among parental tumor tissues, organoids and ODX, while PAX8 and CA‐IX expressions were specific to organoid and ODX only." (PMID 38923304, 2024). "ASPSCR1::TFE3 ChIP-seq on mouse tumor cells and patient-derived cells determined that the fusion oncoprotein highly colocalized with the active histone mark H3K27ac and bound near genes related to blood vessel development." (PMID 38916046, 2024). "This study aims to elucidate the functional consequences of ARID2 deficiency in TFE3-RCC, investigating its impact on tumor biology, gene expression patterns, molecular mechanism, and potential therapeutic targets." (PMID 39727945, 2024).
tumor (continued). "As malignant tumours of mesenchymal origin, alveolar soft tissues are diffusely and strongly positive (nuclear expression) for the transcription factor E3 (TFE3) gene." (PMID 38872175, 2024). "Through a series of in vitro and in vivo experiments, we confirmed that ARID2 acts as a tumor suppressor in TFE3-RCC." (PMID 39727945, 2024). "Collectively, juvenile Xp11.2-translocation RCC with TFE3 gene fusion is a highly malignant form of the disease, characterized by rapid progression in the short term, resulting in distant metastasis and tumor enlargement." (PMID 38953008, 2024). "Although still controversial, there is increasing evidence that TFE3‐rearranged RCC is a more aggressive tumor." (PMID 38477529, 2024). "The tumour displayed typical morphological alveolar aspect, as well as immunohistochemical profile notably TFE3 nuclear staining." (PMID 38643139, 2024). "Mouse tumor presentation remained consistent even when ASPSCR1::TFE3 was expressed under a tissue-specific promoter." (PMID 38916046, 2024). "Given the positive impact of local lymph node invasion on tumor progression, we strongly recommend that surgeons perform regional lymph node dissection for such TFE3-RCC patients." (PMID 38261736, 2024). "Tumor cells showed widespread membrane positivity for ALK-IHC with positive expression of transcription factor E3 (TFE3)-IHC." (PMID 39205743, 2024). "The present study demonstrates the essential role of the ASPSCR1::TFE3 driven pathways in tumor development and angiogenesis." (PMID 37029109, 2023). "Immunohistochemically, the tumor cells showed diffuse positivity for TFE3, CD10, vimentin, and IFITM1." (PMID 36707859, 2023). "Tumor-derived cell lines have been established from human TFE3-RCC providing useful models for preclinical studies." (PMID 37095531, 2023). "ASPSCR1::TFE3 also upregulates genes important for angiogenesis and tumor metastasis, such as PDGFB, ANGPTL2, and GPNMB17,24,25, suggesting that ASPSCR1::TFE3 plays a central role in the angiogenesis characteristic of ASPS." (PMID 37029109, 2023). "As shown by ASPSCR1::TFE3-expression loss and JQ1 treatment, tumor-growth suppression by each knockout cell was accompanied by significant angiogenic inhibition." (PMID 37029109, 2023). "During 5 days of co-culturing, significant HUVEC sprouting toward the tumor spheroids of ASPS cells occurred; however, the sprouting effect was significantly suppressed by Rab27a or Sytl2 knockout and ASPSCR1::TFE3-expression loss." (PMID 37029109, 2023). "This subtype is characterized by chromosome translocations involving the TFE3 gene and it is an invasive tumor with a poor prognosis." (PMID 38145031, 2023). "TFE3 gene amplification should be distinguished from multiple signals in multinucleated giant tumor cells." (PMID 36740682, 2023). "In ASPS, the TFE3 fusion protein can lead to an increase in lactic acid in the tumor microenvironment." (PMID 36906611, 2023). "This not only correlates with the characteristic cytoplasmic findings, but it also explains the tumor’s positive immunohistochemical staining for TFE3 and wild-type MITF, as lysosomal inhibition induces activation of transcription factors MITF, TFE3, and TFEB." (PMID 37958362, 2023). "MiT family translocation-positive RCC is a rare tumour that harbours gene fusions involving TFE3 or TFEB but accounts for approximately 40% of paediatric RCC and less than 5% of adult RCC10,11." (PMID 38104198, 2023). "Our cases suggest that a high SUVmax of the primary tumour is a clinical characteristic of TFE3-rearranged RCCs." (PMID 37789903, 2023). "We first performed immunostaining on RENCA xenograft tumor sections generated from control or TFE3-KD RENCA cells." (PMID 36935008, 2023). "TFE3-RCC tumor derived cell lines and their tissues of origin were characterized by IHC and gene expression analyses." (PMID 37095531, 2023).
tumor (continued). "Previous studies revealed the significance of YAP1 and TFE3 for carcinogenesis in several tumor entities, such as liver cancer, breast cancer, prostate cancer or renal cancer." (PMID 36749424, 2023). "The YAP1::TFE3 fusion was identified in one case (#130), and this tumour demonstrated unique morphology compared to tumours harbouring the more common WWTR1::CAMTA1 fusion." (PMID 37686662, 2023). "In our previous research, the high-level expression of NMRK2 in TFE3 rRCC facilitates mitochondrial respiration and tumor progression." (PMID 37770905, 2023). "TFE3 enables tumor cells to obtain sufficient energy by activating the autophagy and mTOR signaling pathways." (PMID 36906611, 2023). "The efficacy of PI3K/mTOR inhibitors against TFE3-fusion RCC cell lines confirms the importance of the mTOR pathway as a driver of tumor cell growth." (PMID 37095531, 2023). "Overexpression of the fused of the TFE3 gene facilitates tumor progression and this is also a typical feature of the Xp11.2 translocation RCCs." (PMID 36276115, 2022). "Pathology revealed that the tumor cells were positive for TFE3 immunohistologically and positive for TFE3 break-apart fluorescence in situ hybridization assay." (PMID 36034832, 2022). "Despite the progress reviewed here, it remains difficult to disentangle the cellular roles of FNIP1/2 in the regulation of AMPK and TFE3 from that of FLCN tumor suppressive function." (PMID 35883484, 2022). "This study suggests that it is necessary to monitor the sensitivity of the tumor to sunitinib in some mRCC patients with high expression of TFE3 or TFEB." (PMID 33637706, 2021). "All four neoplasms with known TFE3 immunohistochemistry and the TFE3 split FISH assay were analyzed by RNA sequencing for fusion partners." (PMID 34917511, 2021). "As a result of these translocations, the expression of the TFE3 fusion protein increases in the nuclei of tumor cells." (PMID 34917511, 2021). "Here, the authors perform genomic and transcriptomic profiling of 63 untreated primary TFE3-tRCC tumours and reveal potential therapeutic targets." (PMID 34489456, 2021). "In these neoplasms the characteristic cytogenetic change is the translocation involving the MIT family transcription factor TFE3 gene." (PMID 31955345, 2020). "Immunohistochemically, the tumor cells were positive for transcription factor E3 (TFE3) (which confirmed the histological diagnosis of ASPS), myogenic determination factor 1 (MyoD1), and (focal) PAS-D, with negativity for desmin and synaptophysin." (PMID 32000418, 2020). "The tumours of patient 3 were positive for TFE-3, INL-1, CD34, Desmin, and Ki67(ranging from 10 to 20% positivity), indicating the proliferative potential of ASPS." (PMID 32085747, 2020). "This indicated that TFE3 can be at least another potent tumour promotor beyond TFEB in specific tumour types such as ccRCC." (PMID 33145941, 2020). "FISH analysis is an accurate and effective approach for the screening and confirmation of this tumor in the presence of uncertain TFE3 expression." (PMID 31828108, 2019). "Subsequently, RNA sequencing confirmed a fusion of MED15 gene exon 11 on chromosome 22 with TFE3 gene exon 6 in the tumor." (PMID 31828108, 2019). "Although both tumours seem to be hypovascular, a previous study showed that the attenuation values of Xp11.2/TFE3 RCC in the corticomedullary phase and early excretory phase were higher than that of pRCC." (PMID 31892340, 2019). "Immunohistochemistry was performed on all the 3 tumors, revealing that the tumor cells were positive for TFE3 and Melan-A." (PMID 29901594, 2018). "The TFE3 gene showed gene splitting in 71.55% of 130 neoplastic cells and in 76.82% of 233 neoplastic cells in the present and the previous tumor, respectively." (PMID 30458744, 2018). "More than 70% of the tumor cells in the present right tumor were strongly positive for transcription factor E3 (TFE3) expression by immunohistochemical analysis with an anti-TFE3 antibody." (PMID 30458744, 2018).